FHL5 (four and a half LIM domains 5)
Description:
May be involved in the regulation of spermatogenesis. Stimulates CREM transcriptional activity in a phosphorylation-independent manner.
Synonyms: FHL-5; ACT; FLJ33049; dJ393D12.2; 1700027G07Rik
Tractability: PROTAC: ubiquitination databases record sites on it.
Gene: Protein-coding gene on chromosome 6 (96,562,548 to 96,619,616, forward strand). Ensembl gene ENSG00000112214.
Subcellular location: Nucleus
Gene Ontology:
Molecular function: protein binding; transcription coactivator activity
Biological process: positive regulation of transcription by RNA polymerase II
Cellular component: nucleus; Z disc
Genetic constraint (gnomAD): Loss-of-function variants: 26 observed, 25.65 expected, observed/expected ratio (o/e) 1.01, 90% interval 0.74 to 1.41. The upper end of that interval is the gene's LOEUF score, 1.41, which puts it in group 5 of 6, group 1 being the genes least tolerant of losing a copy. Missense variants: 278 observed, 302.12 expected, observed/expected ratio (o/e) 0.92, 90% interval 0.83 to 1.02. Synonymous variants: 92 observed, 97.92 expected, observed/expected ratio (o/e) 0.94, 90% interval 0.79 to 1.12.
Homologues: Orthologues: chimpanzee FHL5 (99% identical), macaque FHL5 (98% identical), dog FHL5 (89% identical), pig FHL5 (89% identical), rabbit FHL5 (88% identical), guinea pig FHL5 (87% identical), rat Fhl5 (87% identical), mouse Fhl5 (85% identical), tropical clawed frog fhl5 (60% identical), zebrafish fhl5 (60% identical), Caenorhabditis elegans lim-9 (47% identical). Paralogues in human: FHL2 (59% identical), FHL3 (46% identical).
Diseases named in the same sentence as FHL5 in open-access papers:
FHL5 is named in the same sentence as 34 diseases in open-access papers, as found by Europe PMC text mining. Sharing a sentence is not in itself a finding about the gene and the disease. The quoted sentences say what the papers report.
migraine (19 papers, 2014 to 2024). "Given that MO is the most common subtype of migraine, we conducted this case–control study to evaluate the associations of FHL5 and KCNK5 genes with the risk of MO in a Han Chinese population." (PMID 33762637, 2021). "In that study, two additional established migraine risk variants, rs11172113 in LRP1 and rs13208321 in FHL5, showed suggestive evidence for association to cervical artery dissection, with the same effect direction as for migraine." (PMID 28957430, 2017). "In conclusion, our findings indicated that the T allele carriers of SNP rs10456100 and rs7775721 would increase the risk of MO in a Han Chinese population, providing evidence indicating that the KCNK5 and FHL5 genes contribute to the susceptibility of migraine." (PMID 33762637, 2021). "In our study, substantially elevated SNP-based heritability and replicable top hits in risk loci of PRDM16, FHL5, ASTN2, STAT6/LRP1, SLC24A3 genes were found among migraine-first patients." (PMID 39333847, 2024). "A recent genome-wide meta study suggested that rs67338227 in the FHL5 gene and rs10456100 in the KCNK5 gene are associated with migraine from 27 population-based cohorts excluding Chinese population." (PMID 33762637, 2021). "Our aim was to systematically investigate the relationship of common variants in FHL5 and KCNK5 genes with the susceptibility to MO and provide clues as to the nature of the mechanisms involved in the etiology of migraine." (PMID 33762637, 2021). "A recent GWA meta study suggested that rs67338227 in the FHL5 gene and rs10456100 in the KCNK5 gene are associated with migraine from 27 population-based cohorts excluding Chinese population." (PMID 33762637, 2021). "We found significant associations with migraine for 47 genes, with the strongest association for STAT6 (P = 1.24 × 10−23), followed by UFL1 (P = 7.26 × 10−19), and FHL5 (P = 1.25 × 10−18)." (PMID 34294844, 2021). "Loci mapping to the END1/PHACTR1, LRP1, and FHL5 genes in particular are shared by migraine and CAD or cervical artery dissection." (PMID 32632093, 2020). "Since our results are of GWAS significance, the genes (such as LRP1 and FHL5) identified for migraine by other GWAS are also promising candidate genes for tension-type headache." (PMID 29397368, 2018). "Furthermore, the subtype analysis in this meta-analysis concluded that migraine without aura (MO) was significantly associated with seven genetic loci: near TSPAN2, TRPM8, PHACTR1, FHL5, ASTN2, FGF6, and LRP1." (PMID 39850553, 2024). "For its multiple polyadenylation sites, FHL5 gene may stimulates vascular smooth muscle proliferation and migration via cAMP activation regulation to result in migraine." (PMID 33762637, 2021). "Given that migraine without aura (MO) is the most common subtype of migraine, our aim was to systematically investigate the relationship of common variants in FHL5 and KCNK5 genes with the susceptibility to MO and provide clues as to the nature of the mechanisms involved in the etiology of migraine." (PMID 33762637, 2021). "Hence, vascular etiologies play significant roles in common migraine, and the genes implicated in vascular function could also be associated with migraine susceptibility, including the four-and-a-half LIM domains protein 5 (FHL5) gene." (PMID 33762637, 2021). "For cervical artery dissection, there also appears to be overlap with migraine at two more loci (LRP1 and FHL5), suggesting the possibility of partially shared genetic components between migraine and these diseases." (PMID 27543003, 2016). "Whereas seven loci (i.e. near TSPAN2, TRPM8, PHACTR1, FHL5, ASTN2, near FGF6, and LRP1) were associated with migraine without aura (in a sample of 8348 cases and 139,622 controls), none were associated with migraine with aura (6332 cases vs. 144,883 controls)." (PMID 32503413, 2020).
migraine (continued). "Recently, genome-wide studies have provided new insights for genes associated with migraine disease (the ion channel gene, TRPM8, FHL5, ASTN2, and LRP1 but UTS2 gene was not one of them." (PMID 27090416, 2016). "However, the 2016 finding by no means suggests that a neuronal origin of migraine is now excluded, already because at least five genes (PRDM16, MEF2D, FHL5, ASTN2, LRP1) (also) have a neuronal function." (PMID 30634909, 2019).
Cluster headache (3 papers, 2021 to 2025). A type of headache characterized by repeated attacks of unilateral pain lasting 15 to 180 minutes and associated with local autonomic signs. "The four cluster headache susceptibility loci that were identified by this GWAS were rs113658130 near LINC01877/SATB2 (SATB homeobox 2), rs4519530 in MERTK, rs12121134 near LINC01705/DUSP10 (Dual Specificity Phosphatase 10), and rs11153082 in FHL5." (PMID 39560176, 2025).
coronary artery disease (2 papers, 2024 to 2025). "Among those genes associated with coronary artery disease and myocardial infarction in humans and those with more altered base pairs/variants in Ossabaw than in Göttingen minipigs, two, namely, FHL5 and GUCY1A3, are associated with vasomotor function." (PMID 38133620, 2024). "FHL5 has recently been identified as a candidate gene in coronary artery disease and myocardial infarction, suggesting its involvement in vascular remodeling and disease risk through transcriptional regulation of downstream gene programs." (PMID 40831931, 2025).
Griscelli syndrome type 2 (2 papers, 2018 to 2023). Griscelli syndrome type 2 (GS2) is a rare, inherited condition that affects the skin, hair, and immune system. "The following FHL subtypes have been described: FHL-2 due to mutations in PRF1, FHL-3 (UNC13D), FHL-4 (STX11), FHL-5 (STXBP2), Griscelli Syndrome type 2 (RAB27A) and Chediack-Higashi syndrome (LYST)." (PMID 37426667, 2023). "In 13 out of the 24 (52%) a genetic diagnosis was achieved: PRF1 n = 4 (FHL2), STX11 n = 2 (FHL4), and STXBP2 n = 4 (FHL5), RAB27A n = 2 (Griscelli syndrome type 2), BIRC4 n = 1 (XIAP)." (PMID 30697212, 2018). "Since then, the study of familial cases allowed the recognition of genetic alterations directly affecting proteins involved in cytotoxic activity, such as Munc13-4 (FHL-3), Syntaxin 11 (FHL-4), Munc18-2 (FHL-5), RAB27A (Griscelli Syndrome type 2, GS2), LYST (Chediak-Higashi Syndrome, CHS)." (PMID 37426667, 2023).
breast carcinoma (1 paper, 2022). "Importantly, those genes, such as Peli2 and Fhl5, were found to be simultaneously down-regulated in breast cancers." (PMID 35180880, 2022).
leukemia (1 paper, 2022). A malignant (clonal) hematologic disorder, involving hematopoietic stem cells and characterized by the presence of primitive or atypical myeloid or lymphoid cells in the bone marrow and the blood. "FHL5 (ACT) is also limited to the murine testis and expressed in a group of human tumors, including leukemia, melanoma, and squamous cell carcinoma cell lines." (PMID 35686099, 2022).
Stroke (1 paper, 2020). Sudden impairment of blood flow to a part of the brain due to occlusion or rupture of an artery to the brain. "We identified colocalization signals at several established single trait loci such as TCF21, ADAMTS7, and LIPA for CAD, and NGF, FHL5, TSPAN2, and SLC24A3 for stroke." (PMID 31917787, 2020).
uterine tumor (1 paper, 2025). "Our study showed the consistent downregulation of FHL5 in uterine tumor tissues, with significant association with poor prognosis." (PMID 40831931, 2025).
tumor (2 papers, 2022 to 2025). "This suggests a potential involvement of FHL5 in regulating the tumor microenvironment or suppressing tumor cell proliferation, warranting further functional investigation." (PMID 40831931, 2025). "In line with mRNA-level changes, protein levels of ABLIM1, FHL5, and MAP3K8 decreased progressively from normal tissue to tumor tissues, whereas TOP2A showed an opposite trend." (PMID 40831931, 2025). "Our analyses unveiled four hub genes—ABLIM1, FHL5, MAP3K8, and TOP2A—that consistently emerged as differentially expressed across all tumor samples when compared to normal tissue." (PMID 40831931, 2025). "ABLIM1, FHL5, and MAP3K8, on the other hand, were downregulated in ULMS, indicating their potential tumor-suppressive roles." (PMID 40831931, 2025). "Four hub genes—ABLIM1, FHL5, MAP3K8, and TOP2A—were consistently dysregulated in both tumor types relative to normal tissue, suggesting their common role in tumor development." (PMID 40831931, 2025).
cancer (1 paper, 2025). A tumor composed of atypical neoplastic, often pleomorphic cells that invade other tissues. "In contrast to TOP2A, the remaining three genes—ABLIM1, FHL5, and MAP3K8—exhibit more context-dependent roles in cancers." (PMID 40831931, 2025).
FHL5 also shares sentences with these, for which no sentence is quoted: migraine without aura (2 papers); myocardial infarction (2); atherosclerosis (1); brain aneurysm (1); Chediak-Higashi syndrome (1); chronic fatigue syndrome (1); chronic granulomatous disease (1); cutaneous T-cell lymphoma (1); familial isolated dilated cardiomyopathy (1); generalized epilepsy (1); Headache (1); infertile (1); male infertility (1); melanoma (1); Obesity (1); panic disorder (1); personality disorder (1); prostate carcinoma (1); Pseudoxanthoma elasticum (1); rhabdomyosarcoma (1); Sezary syndrome (1); squamous cell carcinoma (1); Tension-type headache (1); Wolman disease (1).